TRAF6 (TNF receptor associated factor 6)
Diseases named in the same sentence as TRAF6 in open-access papers (continued):
Sharing a sentence is not in itself a finding about the gene and the disease.
cancer (continued). "EGCG’s binding to tumor necrosis factor receptor-associated factor TRAF6, especially to specific amino acids like Gln54, Asp57, and Ile72, significantly attenuates TRAF6’s E3 ubiquitin ligase activity, contributing to cancer prevention." (PMID 38611299, 2024). "At present, several studies are endeavoring to discover drugs that inhibit the activity of TRAF6-dependent enzymes in combination with radiation therapy or immunotherapy to control cancer development." (PMID 38169510, 2024). "Mechanistically, knocking down TRAF4, TRAF5, or TRAF6 in retinoic acid-treated cancer cell lines increased the levels of procaspase 9 and induced cell apoptosis." (PMID 37389738, 2023). "Specifically, TRAF7 exhibited the highest average mRNA level among the TRAF family, followed by TRAF4, while TRAF6 showed the lowest average mRNA level according to the TCGA cancer database." (PMID 37389738, 2023). "TRAF6 has been confirmed recently to be a prognostic biomarker that is likely to overexpress in such cancers as pancreatic cancer, renal cell carcinoma, and colorectal cancer." (PMID 37746908, 2023). "TRAF6, an E3 ubiquitin ligase, is well recognized to overexpress in various types of cancer, which predicts a poor prognosis." (PMID 37746908, 2023). "TRAF-6 expression is increased in several models of muscle atrophy, including fasting and cancer, leading to the downstream activation of major catabolic pathways in skeletal muscle, including autophagy." (PMID 36835176, 2023). "The expression of miR-146a is altered in various cancers and reportedly targets IRAK1 and TRAF6, leading to the inactivation of the inflammatory, tumorigenic NF-kB signaling pathway, apoptosis stimulation, and cancer cell proliferation reduction." (PMID 37711209, 2023). "Abnormal overexpression and gene amplification of TRAF4 and TRAF6 in human carcinomas have been observed to disrupt cell migration, potentially contributing to cancer development." (PMID 37389738, 2023). "Our results demonstrate that TRAF6 stabilizes PD-L1 and upregulates the MHC-I-dependent antigen presentation, suggesting that TRAF6 is directly involved in cancer immunotherapy." (PMID 35361799, 2022). "Although the function of TRAF6 in inflammation and cancer progression has been widely studied, its role in paclitaxel sensitivity remains to be examined." (PMID 35194034, 2022). "Recent findings suggest that TRAF6 regulates tumorigenesis by inhibiting apoptosis and stimulating the proliferation and invasion of various cancers." (PMID 36298765, 2022). "We have found that TβRI undergoes proteolytic cleavage in cancer cells in a manner dependent on TRAF6 and the active γ-secretase complex leading to the generation of TβRI-ICD." (PMID 35853811, 2022). "In cancer cells, TRAF6 also engages and activates proteolytic enzymes such as ADAM17/TACE and presenilin-1 (PSEN1 or PS1), which leads to the generation and release of the TGFβRI intracellular domain (TGFβRI-ICD)." (PMID 35625561, 2022). "For instance, IL-17B/IL-17RB signaling pathway leads to malignant transformation of cancer stem cells via promoting binding of TRAF6 to Beclin-1 and its K63-mediated ubiquitination." (PMID 36202787, 2022). "TRAF6 promotes oncogenesis by inhibiting apoptosis and stimulating the proliferation and invasion of cancer cells." (PMID 35956111, 2022). "TRAF6 interacts with p62 and activates mTORC1 by catalyzing its K63 ubiquitination, which regulate autophagy and cancer cell growth." (PMID 36202787, 2022). "TRIM37 has been reported to interact with TRAF2 and TRAF6 to promote cancer cell proliferation and chemoresistance." (PMID 35163097, 2022). "Our data shows that TRAF6-induced K63-linked polyubiquitination on K85 and K87 in the beginning of kinase domain of AURKB occurs during mitotic progression of cancer cells when AURKB is active." (PMID 35853811, 2022).
cancer (continued). "The experimental results confirmed that CCL3 can promote the proliferation of cancer cells, and its expression is closely related to TRAF6/NF-κBmolecular pathway." (PMID 35935327, 2022). "For instance, peroxiredoxin 1, an antioxidant enzyme, was observed to inhibit TRAF6 ubiquitin-ligase activity, downregulate autophagy and inhibit cancer cell migration." (PMID 34760883, 2021). "It has been reported that USP4 can deubiquitinate and stabilize TRAF2/TRAF6 to inhibit TNFα-induced cancer cell migration." (PMID 32549341, 2020). "As a RING domain-containing E3, TRAF6 affects different signaling pathways involved in cancer, and high expression of TRAF6 leads to poor prognosis of various tumors." (PMID 32905356, 2020). "Recent studies have indicated that TRAF6 regulates tumorigenesis by inhibiting apoptosis and stimulating proliferation and invasion in various cancers, including PDAC 26-29." (PMID 32226532, 2020). "In this report, we identified that HIF-1β, via the control of TRAF6, is required for full activation of NF-κB signalling in human cancer cell models." (PMID 32344511, 2020). "This review summarizes the functional roles of TRAF6 in regulating immunocytes and in the pathogenesis of ADs and cancer as well as the possibility of TRAF6 as a potential promising target for future AD and cancer treatment." (PMID 33294443, 2020). "In view of the dynamic interaction between cancer cells and the microenvironment, it is important to consider how the expression of TRAF6 in immune cells affects cancer progression." (PMID 33294443, 2020). "Our results demonstrate the importance of TRAF6 in cell survival, following NF-κB stimulation, in cancer cells." (PMID 32344511, 2020). "The TRAF6 protein levels were decreased in human NSCLC cancer tissues compared with the paired paracancerous tissues, and were lower in NSCLC cell lines than in the human bronchial epithelium cell line (HBE)." (PMID 33015045, 2020). "TRAF2 is similar to TRAF6 and plays an important role in inflammation, immune response, and malignant tumor infiltration." (PMID 33456463, 2020). "Mechanistically, we identified TRAF6 as a gene specifically regulated by HIF-1β not only in human cancer cells but also in Drosophila melanogaster." (PMID 32344511, 2020). "The E3 ligase TRAF6-, TRAF4-, and Skp2-mediated K63-linked ubiquitination of AKT is required for AKT activation in human cancer cells." (PMID 32357935, 2020). "Overexpression of TRAF6 sufficiently reversed miR-146a-5p-induced cancer cell proliferation, migration, and apoptosis resistance." (PMID 33015045, 2020). "Previous findings revealed that miR345-3p targets TRAF6 in endothelial cells, while its roles in cancer development hasn’t been reported." (PMID 32699526, 2020). "Although only certain cancer cell phenotypes were examined, the present work showed that a simple intervention of TRAF6 was sufficient to reverse the malignant behavior of the NSCLC cell lines." (PMID 33015045, 2020). "TRAF6 is also regulated by several cancer-related miRNAs, particularly miR-146a, which negatively regulates TRAF6 expression." (PMID 30643010, 2019). "Our results present a compelling case for TRAF6 as a potential therapeutic target in anti‐cancer immunotherapies." (PMID 30886050, 2019). "To investigate the role of TRAF6 in SCCHN, we analysed TRAF6 mRNA expression level from the publicly available cancer microarray database Oncomine®." (PMID 29193723, 2018). "Gain-of-function alterations (gene amplification and overexpression) are common for TRAF1, TRAF4, TRAF5, and TRAF6 in human cancers, and are also identified for TRAF2 in epithelial cancers." (PMID 30294322, 2018). "We also demonstrated that TRAF6 is closely associated with EMT process and cancer stem cells using a Tgfbr1/Pten 2cKO mice SCCHN model and human SCCHN tissue microarray." (PMID 29193723, 2018). "Recent studies have reported that TRAF6 promotes oncogenesis by inhibiting apoptosis and stimulating proliferation and invasion in cancer." (PMID 29463844, 2018).
cancer (continued). "Deep deletion of TRAF6 is less common but also detected in several different types of human cancers." (PMID 30294322, 2018). "Recently, TRAF6 has also been corroborated to be an oncoprotein involved in cancer development and progression in multiple cancers." (PMID 29703234, 2018). "Recently, studies have increasingly demonstrated that TRAF6 plays vital roles in the tumorigenesis and development of multiple cancers, including CRC43–47." (PMID 29855462, 2018). "Remarkably, TNF receptor-associated factor 6 (TRAF6) has been justified as a lead target of miR-146b-5p in HCC and miR-146b-5p applies the cancer obliteration functions through repressing phosphorylation of Akt mediated by TRAF6." (PMID 30564069, 2018). "The multiple anti-cancer functions of miR-146b-5p were due to the inhibition of the TRAF6/p-Akt pathway." (PMID 28404923, 2017). "In this study, we chose the RING domain of TRAF6, because it is the binding domain for Ubc13 and represents a potential therapeutic target for cancers." (PMID 28231796, 2017). "TRAF6 ubiquitination has been demonstrated to mediate human microvascular endothelial cell sprouting and cancer angiogenesis." (PMID 29081889, 2017). "TRAF6 proteins can be treated as drug target proteins for a differentiation therapy against cancers." (PMID 25089269, 2014). "Recent studies indicate that the overexpression of TRAF6 can induce a fatal acute myeloid leukemia and several human cancer types." (PMID 25089269, 2014). "This study aims to investigate the potent lead TCM candidates for TRAF6 protein inhibitors against cancers." (PMID 25089269, 2014). "We also analyze the expression of TRAF6 in 8 muscles of control and cancer patients by western blotting, the results show the expression of TRAF6 in muscle of cancer patients were higher than control." (PMID 23013936, 2012). "Muscle-specific depletion of TRAF6 preserves skeletal muscle mass in a mouse model of cancer cachexia or denervation." (PMID 23013936, 2012). "The identification of TRAF6 by the proposed network-based biomarker approach reinforces the linkage between inflammation and cancer." (PMID 21211025, 2011). "Moreover, TRAF6 was found to exert inhibitory effects on cancer progression in KIRC (OS: n = 531, p < 0.001) and READ (OS: n = 158, p = 0.049)." (PMID 38825674, 2024). "Therefore, therapeutically targeting TRAF6 represents a promising strategy for cancer treatment and overcoming drug resistance." (PMID 39706834, 2024). "Moreover, TRAF6 regulates autophagy by interacting with P62 and activating mTORC1, thereby significantly contributing to cancer cell proliferation." (PMID 38169510, 2024). "Collectively, these studies showed that TRAF6 can target c-Myc-driven cancer cells." (PMID 39243105, 2024). "Employing a rigorous and systematic approach, we comprehensively evaluate the functional repertoire and potential roles of TRAF6 in various cancer types, thus highlighting TRAF6 as a compelling and emerging therapeutic target worthy of further investigation and development." (PMID 38169510, 2024). "Therefore, our findings uncovered the underlying mechanism of TRAF6 to facilitate chemoresistance in TNBC, which can provide a potential therapeutic target for cancer treatment." (PMID 37746908, 2023). "Downregulation of TRAF6 notably increased the apoptosis rate of cancer cells." (PMID 37484971, 2023). "Recent studies indicated that TRAF6 plays an important role in cancer." (PMID 36678795, 2023). "Overall, TRAF6 can be considered an ideal therapeutic target for human cancer, and small molecules targeting TRAF6 may be considered as potential or adjuvant agents for cancer therapy." (PMID 36769122, 2023). "In addition, overexpression of TRAF6 can not only inhibit apoptosis of various types of cancer cells but also promote cancer cell proliferation." (PMID 36604411, 2023).
cancer (continued). "We also demonstrated that inhibiting TRAF4, TRAF5, or TRAF6 could suppress cancer cell proliferation, highlighting the critical oncogenic role of TRAFs in carcinogenesis." (PMID 37389738, 2023). "Studies have shown that TRAF6 is highly expressed in malignant tumors." (PMID 36604411, 2023). "Although several studies have investigated the role of TRAF6 in different cancers, its regulatory role in the crosstalk between apoptosis and autophagy remains unknown." (PMID 37484971, 2023). "Finally, the Chincona alkaloid has been shown to bind to the RING domain of TRAF6 and to promote the apoptosis of cancer cells." (PMID 36769122, 2023). "For further reading about the oncogenic role of TRAF6 in cancer, see a recent review." (PMID 35625561, 2022). "Here, we focus on the role of TRAF6 in promoting certain cellular responses in cancer cells." (PMID 35625561, 2022). "In the non-canonical signaling pathway, TNF receptor-associated factor 6 (TRAF6) has been shown to play important key roles in the diversity of the effects of the TGF-β signaling pathway in cancer cells, leading to either apoptosis or EMT." (PMID 35625561, 2022). "When TRAF6 is overexpressed, it confers at least three known cancer hallmarks, including maintenance of proliferative signaling, resistance to cell death, and induction of angiogenesis, in pancreatic and breast cancers." (PMID 36298765, 2022). "When cancer patients had high TRAF6 expression, a higher level of CTL indicated a better survival." (PMID 35361799, 2022). "TRAF6 has oncogenic characteristics involved in cancer progression." (PMID 35422093, 2022). "In addition, dysregulated expression of cellular proteins, as it occurs in cancer, can lead to TRAF6 degradation." (PMID 34298830, 2021). "Besides the genes encoding ZAPs, we also detected five genes encoding signaling molecules involved in the immune response to cancer, namely TRAF6, EIF2AK2, PIK3CA, APAF1, and POU2F2." (PMID 34844636, 2021). "TRAF6 is upregulated in skeletal muscle in response to denervation, starvation and cancer cachexia." (PMID 34572540, 2021). "Furthermore, it is reported that miR-146a can restrict the NF-κB signaling pathway mediated by IRAK1 and TRAF6, which is an important signaling factor involved in the occurrence of cancers." (PMID 33816633, 2021). "Additionally, blocking TRAF6 in mice models of cancer cachexia attenuated autophagy-dependent muscle wasting." (PMID 34760883, 2021). "Moreover, recent studies have indicated that TRAF6 regulates tumorigenesis in various cancers, including PDAC 26,27." (PMID 32226532, 2020). "So we suspected that TRAF6 can be posttranscriptionally modified and molecular weight of TRAF6 may change in complicated cancer tissues." (PMID 32724313, 2020). "The TRAF6 protein can be used as a drug target protein for cancer differentiation therapy." (PMID 33294443, 2020). "Additionally, studies have shown that TRAF6 has an important role in the development of various cancers." (PMID 32436333, 2020). "We identified TRAF6 as the important target gene of miR-146a-5p to promote NSCLC cancer survival." (PMID 33015045, 2020). "TRAF6 is highly expressed in many different types of cancer including colorectal cancer." (PMID 30931933, 2019). "TRAF6 is overexpressed in a variety of cancers including colon cancer." (PMID 30931933, 2019). "We next explored how TRAF6 modulation could affect Treg‐enforced immune suppression in the cancer setting." (PMID 30886050, 2019). "The results show that positive TRAF6 staining was mainly located in the cytoplasm of cancer cells and partially in the nucleus, and its expression was significantly increased in SCCHN (n = 64) versus dysplasia (n = 12, P < 0.05) and normal mucosa tissues (n = 38, P < 0.001)." (PMID 29193723, 2018).
cancer (continued). "To explore whether an association is present between TRAF6 with EMT and cancer stem cells, we first inquired the Tissue Cancer Genome Atlas dataset (TCGA)." (PMID 29193723, 2018). "Furthermore, TRAF3 and TRAF6 are crucial for osteoclast differentiation, and therefore can regulate bone metastasis of various cancers." (PMID 30294322, 2018). "Flow cytometry showed TRAF6 knockdown reduced ALDH1‐positive cancer stem cells." (PMID 29193723, 2018). "Although TRAF6 has been shown to have oncogenic activity in various malignant tumors, the details remain unclear." (PMID 29463844, 2018). "In addition to the TRAF6-NF-κB axis that has been verified in both human cancers and in vivo mouse models, numerous TRAF6-dependent oncogenic pathways have been reported with studies of patient samples, cultured human cancer cells or their xenografts in mice." (PMID 30294322, 2018). "Cancer cells are known to over-express TRAF6 that is critical for both AKT and TAK1 activations." (PMID 28231796, 2017). "In order to explore whether miR-146b-5p performs its anti-cancer role though inhibiting the TRAF6-mediated phosphorylation of Akt, we detected the expression of total Akt (t-Akt) and phosphorylated Akt (p-Akt) in transfected cells." (PMID 28404923, 2017). "Cinchonine, a naturally occurring Cinchona alkaloid identified from the docking study, could bind to TRAF6 in HeLa and A549 cells and induce apoptosis of these cancer cells." (PMID 28231796, 2017). "Since good cell viability is important for cellular material transporting, high expression of TRAF6 might promote cancer growth by keeping cancer cells alive." (PMID 27708550, 2016). "Notably, we demonstrated that Basigin (BSG)/CD147, a critical molecule for cancer cell invasion and metastasis, is a novel interacting partner of TRAF6." (PMID 26769849, 2016). "The positive correlation between TRAF6 and ubiquitin expression suggests that TRAF6 may regulate ubiquitin activity in human cancer cachexia." (PMID 26856534, 2016). "The upregulated p62/TRAF6 signalling promotes cancer cell survival." (PMID 27558312, 2016). "Signalling of p62/TRAF6 has been proposed to play a role in the development of carcinomas." (PMID 27558312, 2016). "Hence, we propose the TCM compounds, diiodotyrosine and saussureamine C, as potential candidates as lead compounds for further study in drug development process with the TRAF6 protein against cancer." (PMID 25089269, 2014). "Taken together, TRAF6 regulates MCL-1 stability in diverse cancer cell lines." (PMID 25340740, 2014). "TRAF6 has recently emerged as an oncogene and is overexpressed in diverse human cancers." (PMID 25340740, 2014). "Hence, we propose the TCM compounds, diiodotyrosine and saussureamine C, as potential candidates as lead compounds for further study in drug development process with the TRAF6 protein against cancers." (PMID 25089269, 2014). "Up to date, few studies have investigated the prognostic role of TRAF6 in human cancers." (PMID 24999832, 2014). "In this case, TRAF6 is critical for TGFβ-induced invasion of cancer cells." (PMID 23758787, 2013). "We found a positive correlation between TRAF6 and ubiquitin expression, suggesting that TRAF6 may up regulates ubiquitin activity in cancer cachexia." (PMID 23013936, 2012). "Thus, TRAF6-induced NF-κB activation within the RANK and toll-like receptor (TLR) pathways is significantly implicated in the advancement and maintenance of cancer cells, particularly in cancers prone to bone metastasis, including breast 9, prostate 10, lung 11, and liver cancers." (PMID 38169510, 2024). "Furthermore, TRAF3 and TRAF6 were equivalently expressed in all the cancer cell lines detected." (PMID 37389738, 2023). "However, in cancer metastasis, it facilitates the miR-7/TRAF6/NF-kB signaling cascade, which renal transplantation rejection might follow this pattern." (PMID 38224029, 2023). "Therefore, TRAF6 represents a promising targeting candidate for cancer immunotherapy." (PMID 36881608, 2023).